MIR4800 (microRNA 4800)
Synonyms: hsa-mir-4800; mir-4800
Gene: MicroRNA gene on chromosome 4 (2,250,077 to 2,250,156, reverse strand). Ensembl gene ENSG00000284276.
Homologues: Orthologues: chimpanzee MIR4800 (100% identical).